VWF (von Willebrand factor)
Diseases named in the same sentence as VWF in open-access papers (continued):
Sharing a sentence is not in itself a finding about the gene and the disease.
chronic kidney disease (17 papers, 2013 to 2026). Impairment of the renal function secondary to chronic kidney damage persisting for three or more months. "sTM was more related to the primary cause of chronic kidney disease (CKD) compared with vWF and IL-6." (PMID 36046203, 2022). "Increased circulating active VWF levels may also be present in other conditions associated with infection and/or inflammation, for instance in chronic kidney disease (submitted)." (PMID 30759116, 2019). "Multiple studies have demonstrated that patients with chronic kidney disease have low levels of VWF multimers." (PMID 37143635, 2023). "The inverse covariation of vWF with ADAMTS-13 has been considered a prothrombotic state in chronic kidney disease." (PMID 34572522, 2021). "Patients suffering from chronic renal failure simultaneously show increased eryptosis rates and increased adherence of their erythrocytes to VWF." (PMID 30026593, 2018). "We show that VWF-erythrocyte binding substantially contributes to microvascular damage during acute or chronic renal failure." (PMID 30026593, 2018). "vWF is known as a marker of endothelial damage, which is increased in chronic kidney disease (CKD)." (PMID 31057027, 2019). "In line with this hypothesis, our research group has recently demonstrated the specific oxidation of Met1606 in VWF purified from samples of patients with chronic kidney disease, another setting characterized by high oxidative stress." (PMID 23383177, 2013). "However, it has to be remarked that the in our previous study the oxidation of VWF was found elevated in patients with chronic renal failure under hemodialysis." (PMID 23383177, 2013). "Chronic kidney disease stage 5 patients in our cohort clearly showed ED as evidenced by decreased UEA1 expression, and increased tissue VEGFR2 and vWF compared to healthy subjects." (PMID 34621749, 2021).
gastric cancer (17 papers, 2015 to 2025). A primary or metastatic malignant neoplasm involving the stomach. "We have shown that plasma vWF was significantly increased in patients with gastric cancer and that its levels were associated with the stage of cancer-cell differentiation and the rate of metastasis." (PMID 29362409, 2018). "Likewise, VWF, encoding von Willebrand factor that is a platelet adhesion glycoprotein, has been widely used as a biomarker in cancer, and it also has been identified as a new therapeutic target in gastric cancer." (PMID 33178362, 2020). "In contrast, VWF expression was significantly altered in other cancer types, except esophageal and gastric cancer." (PMID 40699668, 2025). "Among the enriched pathways related to poor prognosis, five theranostic markers of interest were identified as deregulated and enriched in gastric cancer, including vWF, FN1, THBS1, PCDH7, and F5." (PMID 39456895, 2024). "In this regard, one would expect platelets to play a greater role in promoting vWF-mediated cancer metastasis in patients with gastric cancer." (PMID 29362409, 2018). "In summary, we identified gastric cancer cells expressing vWF and demonstrated its critical role in promoting cancer metastasis through overlapping mechanisms." (PMID 29362409, 2018). "The vWF-mediated homotypic and heterotypic cell–cell interactions promote the pulmonary graft of vWF-overexpressing gastric cancer BGC823 cells in a mouse model." (PMID 29362409, 2018). "We have shown that patients with poorly differentiated and more invasive gastric cancer had higher levels of plasma vWF (, 2)." (PMID 29362409, 2018). "We have studied blood and tissue samples from gastric cancer patients and conducted experiments in vitro and in mouse models to investigate the role of vWF in regulating cancer metastasis." (PMID 29362409, 2018). "Here we report the results of a study designed to detect vWF expression in gastric cancer cells and to examine a role of cancer-cell-derived vWF in promoting gastric cancer development and metastasis." (PMID 29362409, 2018). "More importantly, vWF has been widely used as a biomarker in gastric cancer.However, its functional role in GPL is largely unknown." (PMID 35342404, 2022). "Here we report that gastric cancer cells from patients and cells from two well-established gastric cancer lines express vWF and secrete it into the circulation, upon which it rapidly becomes cell-bound to mediate cancer-cell aggregation and interaction with platelets and endothelial cells." (PMID 29362409, 2018). "We next investigated whether vWF regulated the development and metastasis of gastric cancer using several complementary approaches." (PMID 29362409, 2018). "Representative genes include VWF and EPAS1 that allow for prognosis differentiation in various gastric cancer treatment cohorts as well as response and survival discrimination in immunotherapy." (PMID 39901877, 2025). "Von Willebrand factor (VWF) is a potent regulator of angiogenesis, tumor growth, and metastasis, and gastric cancer-related plasma VWF activity levels are significantly elevated in advanced disease stages." (PMID 37066015, 2023). "In this study, the gastric cancer patients with high expression of CTLA4 and ENTPD2 had a better survival prognosis, with high expression of CLDN6, EMB, GPR15, VWF and AKR1B1 suggesting poor prognosis, which was consistent with previous studies." (PMID 37066015, 2023). "We also identified a group of cells coexpressing VWF and α-SMA in tumor samples by performing immunofluorescence staining of samples from a different cohort of patients with gastric cancer." (PMID 34976204, 2022). "Increasing evidence showed that the increased expression of VWF not only could lead to an increase in the incidence of cancer complications in terms of thrombosis but also interact with various cancer cells, such as those in papillary thyroid carcinoma, osteosarcoma, and gastric cancer." (PMID 34582363, 2021).
gastric cancer (continued). "Yet, the expression pattern of vWF in human gastric cancer (GC) tissues and its relation to clinicopathological features of these cases remains unknown." (PMID 25886574, 2015). "C11_VWF were characterized by co‐expressing marker genes of fibroblasts (COL1A1, FAP, VIM, ACTA2) and endothelial cells (VWF, PECAM1, CLDN5, FLT1, RAMP2), which resembled a subgroup of cells undergoing an EMT transition in gastric cancer." (PMID 38115703, 2023). "VWF, SHC1, and CAP2 have been reported to be elevated in LNM-positive patients with gastric cancer." (PMID 37158593, 2023). "We further show that the clonal gastric cancer BGC823 cells secreted vWF without stimulation, but the secretion was enhanced by stimulating the cells with thrombin." (PMID 29362409, 2018). "The reason for this phenotypic difference between the primary and clonal gastric cancer cells remains to be investigated, but its presence made the study of the biological activity of gastric cancer-derived vWF using the clonal cells difficult and non-representative." (PMID 29362409, 2018).
Thrombocytosis (16 papers, 2011 to 2025). Increased numbers of platelets in the peripheral blood. "In prospective follow-up, while vWF: Ac ≤ 30%, vWF: Ac/Ag ≤ 0.7 and thrombocytosis conferred a higher risk of total (including minor) bleeding events, JAK2V617F VAF of ≥ 50% was the only factor predictive of major and clinically relevant non-major bleeding." (PMID 41085687, 2025). "A paradoxical risk of bleeding in thrombocytosis has been reported in a few studies, which is explained by various causes such as the von Willebrand factor and platelet abnormal function." (PMID 33096782, 2020). "Historically, thrombocytosis >1000 × 109/L was used as a surrogate for predicting the presence of biochemical type 2 AvWS, (indicated by vWF activity:antigen ratio being <60‐70% of normal)." (PMID 40625825, 2025). "This was a prospective study aimed at determining the role of the platelet function test as well as inflammatory markers, vWF:Ag, and vWF:RCo in distinguishing between primary and secondary thrombocytosis." (PMID 31350969, 2019). "Therefore, current recommendations advise assessing von Willebrand factor antigen and function in patients with extreme thrombocytosis, and if AvWD is diagnosed, low-dose aspirin should be withheld." (PMID 41552126, 2025). "In essence, thrombocytosis can induce a qualitative plasma defect in VWF." (PMID 40625825, 2025). "Importantly, these abnormalities and bleeding symptoms are noted to correct when the platelet count is reduced to normal, demonstrating that the VWF defect is secondary to thrombocytosis." (PMID 40625825, 2025). "In practice, not all laboratories can perform multimer analysis readily, so the combination of a low VWF activity and low VWF activity:antigen ratio in a patient with ET with thrombocytosis may point to the diagnosis of AvWS." (PMID 40625825, 2025). "Another potential cause of bleeding regardless of the cause of thrombocytosis is acquired von Willebrand's syndrome (AVWS) due to increased adsorption of large von Willebrand factor (vWF) multimers by the abnormally high number of circulating platelets." (PMID 22084665, 2011). "However this finding was in the line with another case report concerning a hepatocellular carcinoma patient who had extreme thrombocytosis with a low vWF:RCo but high vWF:Ag resulting from antibodies that interfere with the binding of vWF to platelets without causing clearance of the vWF antigen." (PMID 31350969, 2019). "Three of fifteen dogs were thrombocytopenic, three had thrombocytosis, three were hyperfibrinogenemic, one had low vWF:Ag, three had mild prolongations of PT and none had abnormal aPTT." (PMID 35548053, 2022). "We did not provide vWF supplementation since administration of vWF in patients with thrombocytosis can promote severe platelet aggregation." (PMID 33496866, 2021). "Tefferi et Barbui therefore recommended to measure von Willebrand factor (vWF) antigen and a parameter reflecting vWF function (i.e., vWF or ristocetin cofactor activity) in patients with either extreme thrombocytosis or abnormal bleeding irrespective of platelet counts." (PMID 33712866, 2021).
hyperlipidemia (14 papers, 2014 to 2026). "The vWF: Ac assay appears to be less affected by high bilirubin, free hemoglobin, lipidemia, or genetic polymorphism than the vWF: RCo assay, allowing for more reliable screening of AVWS, particularly in the setting of cardiac valve disease and mechanical circulatory support." (PMID 40486828, 2025). "The vWF:Ac assay seems to be less affected by high bilirubin, free hemoglobin, lipidemia or genetic polymorphism than vWF:RCo and, therefore, allows for more reliable screening of avWS with loss of HMW multimers—especially in the setting of heart valve disease and mechanical circulatory support." (PMID 31359325, 2019). "These markers of remote plaque activation were sustained in mice with hyperlipidemia, which can be explained by recent data that indicate that LDL cholesterol enhances the self-association and therefore adhesive capacity of VWF." (PMID 38693516, 2024). "In murine models of hyperlipidemia, the subsequent development of atherosclerotic lesions can be slowed either by inhibiting GPIbα, the platelet ligand for VWF, or by genetic deletion of VWF." (PMID 38693516, 2024). "Moreover, interferences in the assay measuring ADAMTS13 can occur from a high concentration of von Willebrand factor (vWF), hyperlipidemia, hemolysis with plasma free Hb > 2 g/L, and hyperbilirubinemia, and cleavage by other proteases can even complicate identification of TTP." (PMID 29855343, 2018). "We found similar effects on blood vessel formation, as assessed by staining for αSMA and vWF, although tumor hypervascularization in systemic hyperlipidemia was not further increased by initial tumor cell lipid loading." (PMID 31174567, 2019).
Nephropathy (14 papers, 2005 to 2025). A nonspecific term referring to disease or damage of the kidneys. "However, the rise in ADAMTS13 antigen levels was not accompanied by a proportional increase in ADAMTS13 activity, since ADAMTS13 activity/ADAMTS13 Ag ratio was lower and VWF/ADAMTS13 activity ratio was higher in DM1 patients with nephropathy." (PMID 26770985, 2016). "In addition, von Willebrand factor (VWF) levels, a marker of impaired vascular endothelial cell function, have been reported to be higher in diabetic patients than in normal subjects, and even higher in the presence of retinopathy and nephropathy." (PMID 36836781, 2023). "The association between high ADAMTS13 levels with mild and severe renal dysfunction, and with micro and macroalbuminuria may be explained by the presence of a compensatory mechanism, by which ADAMTS13 synthesis is increased due to the marked elevation in VWF plasma levels, as nephropathy progresses." (PMID 26168189, 2015). "Type 2 DM patients with nephropathy had higher vWF antigen levels than those with type 2 DM without albuminuria, impaired glucose tolerance, and a type 2 DM family history." (PMID 37746066, 2023). "Finally, increased concentrations of vWF (von Willebrand Factor) have been detected in patients with ESRD, suggesting a correlation between the coagulation system and thrombogenicity in kidney disease." (PMID 36499242, 2022). "Elevated levels of INF-γ, VWF, ADAMTS13 antigen, D-Dimer, and reduced ADAMTS13 activity/antigen ratio were observed in patients with nephropathy as compared to those without nephropathy (P = 0.001, P < 0.001, P < 0.001, P < 0.001, and P < 0.001, resp)." (PMID 26770985, 2016). "Patients with CKD also presented elevated plasma levels of VWF, ADAMTS13 antigen, ADAMTS13 activity, D-Dimer and VWF/ADAMTS13 activity ratio, and a reduced ADAMTS13 activity/antigen ratio than those without nephropathy (P < 0.001, P < 0.001, P = 0.003, P < 0.001, P = 0.006, and P < 0.001, resp)." (PMID 26770985, 2016).
osteosarcoma (14 papers, 2012 to 2025). A usually aggressive malignant bone-forming mesenchymal neoplasm, predominantly affecting adolescents and young adults. "von Willebrand factor (vWF) is a major procoagulant molecule that was shown to differentiate between metastatic and primary osteosarcoma (OS) tissues and associated with increased metastasis." (PMID 30279208, 2018). "Furthermore, elevated levels of plasma vWF found in a persistent inflammatory state associated with cancer are often considered to come from perturbed endothelial cells and activated platelets, but osteosarcoma cells have been found to also express vWF28,30." (PMID 29362409, 2018). "Recently, some cancer cells, such as gastric adenocarcinoma cells and osteosarcoma cells, have also been found to actively express VWF." (PMID 39282473, 2024). "For instance, VWF released by endothelial cells, when co-cultured with osteosarcoma cells, induces the osteosarcoma cells to undergo epithelial mesenchymal transitioning, which is an essential step in tumor metastasis." (PMID 35327035, 2022). "In this osteosarcoma cell line, VWF showed the typical pseudo-WPB-like localization which is also induced in HEK293 cells after recombinant expression of VWF." (PMID 34572000, 2021). "In a recent study, VWF was recognized as a downstream effector of miR-24, at least in osteosarcoma cells." (PMID 34947800, 2021). "Immunohistochemistry showed that the VWF protein is expressed in osteosarcoma cells in vivo in 13 out of 29 tumor specimens as well as in vitro in SAOS2." (PMID 34572000, 2021). "In these studies, increased levels of VWF in osteosarcoma and hepatocellular carcinoma tumor tissues in situ were demonstrated and associated with increased metastasis and clinicopathologic staging." (PMID 28035064, 2017). "To determine the functional consequences of VWF expression by osteosarcoma and glioma cancer cells, we compared their adhesion ability to EC monolayers under static conditions, shear flow, and in the absence and presence of platelets." (PMID 28035064, 2017). "To further probe the physiological relevance of our in vitro and in vivo results regarding the functional consequences of VWF expression by cancer cells, we analyzed one patient-derived osteosarcoma and three separate brain tumors for VWF expression." (PMID 28035064, 2017). "VWF protein was reported in cultured human osteosarcoma SAOS2 cells, human colorectal SW480 cancer cells, and recently in two hepatocellular carcinoma cell lines HepG2 and BEL7402." (PMID 28035064, 2017). "It has been reported that in osteosarcoma tumors the expression of VWF gets deregulated, potentially leading to metastasis." (PMID 23166660, 2012). "There are some studies on the relationship between MMP9, VWF, and osteosarcoma." (PMID 35814015, 2022). "Upregulated RAB27A, SYTL2, and VWF expression was confirmed in two human ASPS cell lines, ASPS-KY and ASPS1, in comparison with two Ewing sarcomas, two synovial sarcomas, and one osteosarcoma cell line." (PMID 37029109, 2023). "In the study, by the method of bioinformatics analysis, the possible key genes of osteosarcoma including MMP9, FERMT3, CSF1R, and VWF were screened from two microarray datasets, GSE12865 and GSE36001." (PMID 35814015, 2022). "Through the comprehensive integration of GO, KEGG pathway analysis, and Cytoscape software analysis results, four osteosarcoma key genes, MMP9, FERMT3, CSF1R, and VWF, were finally identified." (PMID 35814015, 2022). "To determine whether VWF is expressed in cancer cells, we screened a variety of malignant glioma cell lines, including those prepared from patient-derived glioblastoma tumor samples, as well as two osteosarcoma cell lines SAOS2 and KHOS to detect VWF mRNA and protein." (PMID 28035064, 2017). "Surprisingly, the same study described that the addition of the VWF–FVIII complex alone has a direct anti-apoptotic effect on osteosarcoma cells in the absence of OPG, which was not further characterized." (PMID 34572000, 2021).
osteosarcoma (continued). "However, a few studies have reported VWF detection in cancer cells of non-endothelial origin, including osteosarcoma." (PMID 28035064, 2017). "For exploration of the mechanism of VWF transcriptional activation in cancer cells, we chose to focus on the two osteosarcoma cell lines to provide a pair of VWF expressing (SAOS2) and non-expressing (KHOS) cancer cell lines with similar origin (both osteosarcoma) for comparative analyses." (PMID 28035064, 2017). "Furthermore pro-VWF is not detected in the osteosarcoma cell line lysate electrophoresis." (PMID 35327035, 2022). "VWF knock down in VWF-expressing cancer cells (osteosarcoma SAOS2 and malignant glioma U251), as well as exogenous VWF expression in non-expressing cancer cells (osteosarcoma KHOS), confirmed that increased adhesive capacity was directly and significantly influenced by VWF expression." (PMID 28035064, 2017). "To explore the mechanism of transcriptional activation of the VWF gene in cancer cells, we explored the presence and VWF-chromatin binding pattern of these regulatory trans-acting factors on VWF-expressing (SAOS2) and non-expressing (KHOS) osteosarcoma cell lines." (PMID 28035064, 2017).